UCP2 (uncoupling protein 2)
Diseases named in the same sentence as UCP2 in open-access papers (continued):
Sharing a sentence is not in itself a finding about the gene and the disease.
cancer (continued). "The expression of UCP2 is increased in cancer and in cancer cachexia in response to increasing oxidative stress, the consequence of which is an increase in their apoptotic threshold." (PMID 34680055, 2021). "Overexpression of UCP2 in multiple human cancer cell lines has consistently shown to favor a highly glycolytic phenotype, inhibits ROS accumulation, and prevents apoptosis after exposure to chemotherapeutic agents." (PMID 33763373, 2021). "Overexpression of UCP-2 has been reported in various types of cancers, including HER2-amplified cancers, and is likely to contribute to oxidative stress response, thus related to drug resistance." (PMID 34146128, 2021). "Here we report that the upregulation of UCP2 significantly reduces cancer cells' viability in case of enhanced ER-mitochondrial tethering." (PMID 33614647, 2021). "In contrast, the UCP2 overexpression leads to the uncoupling of mitochondria, which contributes to enhance anaerobic glycolysis in cancer cells." (PMID 32655416, 2020). "BEST1, UCP2 and FXYD1 are genes associated with nutrient and energy transport that have previously been identified as upregulated in cancer cells." (PMID 32051475, 2020). "In cancer cells, UCP2 is generally overexpressed to attenuate ROS formation and to trigger anti-apoptotic properties and resistance to therapies." (PMID 32111081, 2020). "In particular, UCP2 has been strongly related to tumorigenesis since it is involved in cancer cell proliferation and chemoresistance." (PMID 32111081, 2020). "In cancer cells, UCP2 regulates fatty acid oxidation and mitochondrial respiration, as well as tumorigenic properties." (PMID 31932578, 2020). "UCP2 is primarily identified in cells with high synthetic and proliferative activity, such as pluripotent stem, cancer and immune cells, including microglia in the brain." (PMID 31133866, 2019). "Our group and others have recently shown that UCP2 is confined to rapidly proliferating cells that rely on glycolysis, such as stem cells, activated immunological cells, and cancer cells." (PMID 31706565, 2019). "Induction of uncoupling protein 2 (UCP2) has been related to cancer metabolic switch, leading to accelerated glycolysis and reduced mitochondrial activity." (PMID 30538804, 2018). "While UCP1 is predominantly expressed in brown adipocyte tissue, UCP2 is ubiquitously expressed in cancer derived from different tissues." (PMID 30538804, 2018). "In this way, glutamine, an amino acid oxidized by cancer cells, immune cells, pancreatic β-cells, or intestinal epithelium, is related to UCP2 beneficial functions in natural sites of its expression." (PMID 29351723, 2018). "Many other studies on cancer based on UCP2 inhibition and ROS generation by genipin have also been published." (PMID 29587429, 2018). "In this study, we investigated the role of the β3-AR/UCP2 axis on the regulation of the Warburg metabolism in cancer stem cells (CSC) and in mouse embryonic stem cells (ESC)." (PMID 30538804, 2018). "A self-standing topic is represented by the attenuation of superoxide production by UCP2 in cancer cells." (PMID 29351723, 2018). "One of the emerging rational approaches in targeting cancer cells by chemotherapeutic agents as well as in abolishing chemo-resistance is, thus, through UCP2 targeting." (PMID 29587429, 2018). "Such cancer-specific remodeling is given by the UCP2-mediated rerouting of C4 metabolites that also interferes with information signaling." (PMID 29351723, 2018).
cancer (continued). "Inhibition of UCP2 with genipin was suggested to sensitize drug-resistant cancer cells to cytotoxic agents." (PMID 29351723, 2018). "In this study, for the first time, we demonstrate that β3-AR is able to promote this metabolic shift in both cancer and embryonic stem cells, inducing specific glycolytic cytoplasmic enzymes and a sort of mitochondrial dormancy through the induction of UCP2." (PMID 30538804, 2018). "They appear to enhance ROS generation both through the NADPH oxidase system and via the mitochondria, primarily through a UCP2 mechanism in cancer cells." (PMID 29587429, 2018). "UCP2 is known to suppress mitochondrial ROS production and is employed by drug-resistant cancer cells to mitigate oxidative stress." (PMID 29587429, 2018). "Cancer cells with high levels of antioxidant systems and mitochondrial suppressor of ROS (e.g., uncoupling protein-2), have been found to induce chemoresistance in them." (PMID 28955240, 2017). "In human cancers, UCP2 is overexpressed in a number of aggressive cancers including prostate, kidney, thyroid, skin, etc.." (PMID 29221144, 2017). "Genipin is known to be highly selective and specific to UCP2's inhibition and has been shown to sensitize drug-resistant cancer cells by inhibiting the actions of UCP2." (PMID 29221144, 2017). "The metabolite transporter activity of UCP2 provides a strong rationale for the notion that highly expressed UCP2 in cancer cells contributes to the Warburg effect." (PMID 29221144, 2017). "Nevertheless, to ensure sufficient mitochondrial Ca2+ uptake, the uncoupling protein 2 (UCP2) is able to normalize mitochondrial Ca2+ uptake in case of PRMT1-driven methylation of MICU1 in cancer cells." (PMID 29113301, 2017). "Uncoupling protein 2 (UCP2) is an inner mitochondrial membrane transporter which is often upregulated in human cancers." (PMID 29221144, 2017). "UCP2 plays a role in carcinogenesis in various tissues and regulates the responsiveness of carcinomas to chemotherapy." (PMID 28042952, 2017). "When patients were grouped according to UCP2 expression in carcinoma tissues, NSCLC patients with high UCP2 expression levels had longer progression-free survival (PFS) than those with low UCP2 expression." (PMID 28042952, 2017). "UCP2 is known to suppress ROS level which is overexpressed by various types of cancer cells including HCC cell lines." (PMID 27129291, 2016). "UCP2 over-expression is a possible strategy adopted by cancer cells for protection from excess ROS production." (PMID 26771380, 2016). "Overexpression of UCP2 protected cancer cells from the gemcitabine-induced apoptosis through decrease of mitochondrial superoxide." (PMID 26666173, 2015). "Lower level of miR-214 was observed in most of cancer tissues (15/20, 75.0 %), while UCP2 mRNA was significantly upregulated (17/20, 85.0 %) as compared with the matched normal tissues (P = 0.0013 and P = 0.0022, respectively)." (PMID 26666173, 2015). "Previously, it was suggested that UCP2 facilitates the development of tumors by promoting the metabolism of cancer cells." (PMID 24523901, 2014). "In contrast, a UCP2 knockout mouse was found to have had a higher potential of cancer development as the wild type." (PMID 24523901, 2014). "In specimens of human ovarian cancers carboplatin/paclitaxel-resistant cancers showed decreased UCP2 protein abundances as compared to the sensitive ones." (PMID 23966948, 2013). "A good example comes from the cancer field and, thus, it has been shown that UCP2 levels are elevated in drug-resistant tumour cells and that UCP2 inhibitors sensitize cancer cells to chemotherapeutic agents." (PMID 23437414, 2013). "UCP2 over-expression reportedly prevents oxidative injury, thereby possibly contributing to a higher apoptotic threshold assisting survival of cancer cells." (PMID 24027528, 2013).
cancer (continued). "In fact, UCP2 is upregulated in many pathological processes in which ROS play an important role in the development of the disease (atherosclerosis, cancer, chronic inflammation, etc.)." (PMID 23437414, 2013). "Consistent with our results, previous studies have shown that the main function of UCP2 in cancer cells is to regulate ROS production." (PMID 22292025, 2012). "Among the up-regulated genes, UCP2’s expression was predominantly higher in rho0 epithelial cells, cancer cell lines and primary tumors." (PMID 21935467, 2011). "Drug-resistant sub-lines of various cancer cells exhibit increased levels of UCP2, lower mitochondrial membrane potential and diminished susceptibility to cytotoxic effects." (PMID 21712825, 2011). "Compared with the extensive studies on UCP in diabetes and obesity, the role of UCP (mostly UCP2) in cancer was recently recognized and has attracted more attention." (PMID 21954358, 2011). "Since UCP2 is over-expressed in a variety of cancers, we wished to identify a transcriptional regulator of UCP2." (PMID 21935467, 2011). "There should be cautious optimism about UCP2 entering centre stage and becoming a novel therapeutic target in cancer." (PMID 21712825, 2011). "One mechanism of UCP2 upregulation in these cancers is due to oxidative stress, and elevated UCP2 in turn reduces oxidative stress, which provides a growth advantage for these cancers." (PMID 21954358, 2011). "In keeping with the notion that partial breakdown of Δψm is the pivotal mechanism behind the antioxidant and anti-apoptotic effects of UCP2 in cancer cells, many of these effects are reproduced with the use of chemical uncouplers (protonophores)." (PMID 21712825, 2011). "Uncoupling induced by overexpression of UCP2 has been shown to prevent ROS formation, and, in turn, increase apoptotic threshold in cancer cells, providing a pro-survival advantage and a resistance mechanism to cope with ROS-inducing chemotherapeutic agents." (PMID 24281083, 2010). "Nevertheless, inhibition of UCPs, has to be considered as a strategy aimed at promoting the effects of other therapeutic agents, contributing to avoid the anti-apoptotic shield that UCP2 confers to cancer cells." (PMID 24281083, 2010). "More intriguingly, UCP2 overexpression has been suggested to be part of the adaptive mechanism required for the survival of cancer cells in adverse environments." (PMID 20967268, 2010). "One mitochondrial adaptation to increased ROS is over-expression of uncoupling protein 2 (UCP2) which has been reported in a number of human cancer cell lines." (PMID 19480693, 2009). "We have cultured three human primary fibroblast lines and seven human cancer cell lines in media of varying glucose and ketone body content to compare cell growth rates, ATP concentration, and expression of UCP2." (PMID 19480693, 2009). "For example SW48, with the greatest reduction of ATP and cell growth in acetoacetate medium, was a prominent outlier with the least UCP2 expression among the cancer cell lines." (PMID 19480693, 2009). "It was proposed that UCP2 over-expression was an adaptive mechanism that reduced ROS-induced apoptosis among the cancer cells." (PMID 19480693, 2009). "Controls demonstrated normal cell growth and ATP with the lowest density of mitochondrial UCP2 staining while all cancer lines demonstrated proportionally inhibited growth and ATP, and over-expression of UCP2 (p < 0.05)." (PMID 19480693, 2009). "Cancers are among the tissues reported to express UCP2 in much higher concentrations than normal tissues." (PMID 19480693, 2009). "The findings extend the observations of previous investigators and point to a specific kind of mitochondrial abnormality, UCP2 over-expression that under conditions of ketosis is capable of reducing the growth rate of certain cancers." (PMID 19480693, 2009).
cancer (continued). "UCP2 expression displayed variation at 96 h depending on the growth medium (GM vs. G + AcA), but all cancer lines showed higher values in either medium compared with fibroblasts (p < 0.05)." (PMID 19480693, 2009). "However, UCP2’s role in cancer appears context-dependent, with evidence also tumor-suppressive functions." (PMID 40983641, 2025). "Considering that the regulation of UCP2 expression plays an important role in pathological conditions such as cancer, the search for molecules that inhibit its expression could be a strategy for the treatment of this pathology." (PMID 40362341, 2025). "These consistent expression patterns suggest that UCP2 may function as an oncogene in diverse cancer contexts, while UCP1, UCP3, SLC25A27, and SLC25A14 are potentially involved in tumor-suppressive mechanisms." (PMID 41403699, 2025). "In contrast, UCP2 was markedly upregulated across the majority of cancers analyzed." (PMID 41403699, 2025). "Interestingly, although ROS levels are typically moderately elevated in tumor cells, UCP2 appears to play an essential role in maintaining redox homeostasis and supporting cancer cell viability." (PMID 41403699, 2025). "Alternatively, UCP2 can also inhibit the proliferation of cancer cells by increasing ROS production, reprogramming cellular metabolism, or enhancing immunity against cancer." (PMID 40362341, 2025). "In contrast, UCP2 positive expression showed a negative association with poor prognosis in cancer patients." (PMID 41367865, 2025). "Additionally, research has shown the involvement of UCP2 in various pathological conditions, including inflammation, metabolic disorders, cancer, and neurodegenerative diseases." (PMID 38429403, 2024). "UCP2 facilitates the metabolic shift in cancer cells towards Warburg’s aerobic glycolysis." (PMID 38255314, 2024). "Our investigation challenges the initial hypothesis that UCP2 uniformly underpins cancer cell survival under conditions of nutrient deprivation." (PMID 38986826, 2024). "Recently, studies have shown that UCP2 could induce a metabolic shift toward the glycolytic pathway, sustaining the Warburg effect which promotes cancer progression." (PMID 38217303, 2024). "Additionally, this finding highlights the intricate regulatory mechanisms of UCP2, which appear contingent upon the specific metabolic requirements and the microenvironmental context of each cancer cell type." (PMID 38986826, 2024). "The role of UCP2 in cancer metabolic rewiring has been studied extensively." (PMID 39795950, 2024). "Here, we hypothesize that upregulation of UCP2 leads to metabolic flexibility of cancer cells during nutrient deprivation, which drives glycolysis after conversion to pyruvate in the cytosol." (PMID 38986826, 2024). "This study also showed the role of UCP-2 in cancer cell survival and drug resistance." (PMID 36900198, 2023). "UCP2 is the most commonly investigated mitochondrial carrier in cancer and specifically in PDAC." (PMID 36672360, 2023). "In line with these concepts, the discovery that UCP2 is a C4-metabolite carrier that facilitates the export of malate, oxaloacetate, and aspartate from the mitochondrial matrix seems to provide a mechanistic explanation for the role of UCP2 in the metabolic adaptations of cancer cells." (PMID 37175829, 2023). "An in vitro study on human colon cancer, using the HCT116 cell line, showed that the overexpression of UCP-2 protects the cells from apoptosis as well as oxidative stress, while the in vivo data showed resistance to anticancer drugs against HC-16-induced cancer in NCr nu/nu mice." (PMID 36900198, 2023). "UCP2 represses reactive oxygen species (ROS) production by mitochondria, and it is involved in diverse physiological and pathological processes, e.g., the differentiation of stem cells along with cancer." (PMID 37744277, 2023).
cancer (continued). "Since uncoupling protein 2 (UCP2) was overexpressed in cancer cells, the authors suggested that the effect of LiAcAc might have been associated with an inefficient Randle cycle." (PMID 36836894, 2023). "The upregulation of UCP-1, UCP-2, and UCP-3 in BAT and UCP-2 in the skeletal muscle and liver suggested that UCPs were involved in utilizing an excess of fat to induce heat production and thereby increased catabolism and energy expenditure in cancer cachexia." (PMID 36900198, 2023). "Indeed, UCP2 overexpression decreases mitochondrial ROS induction in response to gemcitabine and protects cancer cells from gemcitabine-induced apoptosis, suggesting the potential importance of aspartate-associated drug resistance in cancer cells." (PMID 35011702, 2022). "At translational levels UCP2 is activated by glutamine and inhibited by miRNAs, miR-133a and miR-15a, both considered tumor suppressors and found downregulated in many types of cancer." (PMID 35008407, 2022). "In addition, UCP2 modulates the metabolic demands of cancer cells and thus appears to be an interesting candidate to study the immune reprogramming of tumors." (PMID 36499405, 2022). "Of note, although UCP2 is overexpressed in many cancer types, its expression is not induced by KRAS mutations, since the expression of the G12V mutant in BxPC3, a PDAC cell line carrying the wild-type form of KRAS, did not alter the expression of UCP2." (PMID 35008407, 2022). "Through its transport activity, UCP2 modified the utilization of substrate by cancer cells." (PMID 36499405, 2022). "In addition to mitochondrial uncoupling, recent studies revealed that UCP2 plays an important role in the mitochondrial transport of C4 metabolites for NADPH production required for cancer cell growth." (PMID 35628447, 2022). "The proteomic screening of cancer cells treated with OA has revealed that it downregulates several factors, such as mitochondrial uncoupling protein 2 (UCP2), MMP-2, MMP-9, PKM2, superoxide dismutase 2 (SOD2), hypoxia inducible factor 1 alpha (HIF-1α), and PROX1." (PMID 36139025, 2022). "However, studies in other models of epithelial cancer, such as the skin, breast and lung, show an opposite relationship between UCP2 and cancer proliferation." (PMID 36275699, 2022). "Some studies suggest that UCPs (mainly UCP2) accelerate tumor progression by promoting aerobic glycolysis (Warburg effect) and inhibiting reactive oxygen species (ROS), thereby enhancing the resistance of cancer cells against chemotherapeutic agents." (PMID 35874806, 2022). "Therapeutic targeting of mitochondrial uncoupling protein 2 (UCP2), with the resultant enhancement of ROS production, may increase cancer cell susceptibility to apoptosis." (PMID 35705962, 2022). "UCP-2 and cancer-biology relationship also includes a similar complicated structure." (PMID 34481515, 2021). "Upregulation of UCP2 in cancer leads to chemoresistance by decreasing ROS production." (PMID 33935708, 2021). "Conversely, UCP2 knockout may aide in restoring normal metabolic phenotype and pushing stem-like cancer cells towards differentiation." (PMID 33763373, 2021). "Accordingly, we speculate that an inverse correlation between the expression of UCP2 and proteins stabilizing the mitochondrial-ER contact exists, reflecting an adaptation strategy of cancer cells to prevent mitochondrial Ca2+ overload." (PMID 33614647, 2021). "Investigating the mechanism that induces UCP2 expression in cancer cells is important to understand the function of UCP2, which could aid in cancer treatment." (PMID 33859525, 2021). "In the future, the research on function of UCP2 related to apoptosis in the cancer cell is in need." (PMID 33859525, 2021). "The function of the uncoupling protein 2 (UCP2) is different for each cancer cell." (PMID 33859525, 2021).